JAK1 (Janus kinase 1)
Diseases named in the same sentence as JAK1 in open-access papers (continued):
Sharing a sentence is not in itself a finding about the gene and the disease.
melanoma (continued). "In addition, deletion of genes necessary for IFN-γ signaling (such as IFNGR1, IFNGR2, STAT1, JAK1, and JAK2) have been noted in pre-clinical models of melanoma that can lead to resistance to anti-PD-1/PD-L1 therapies, which might also play a role in acquired resistance." (PMID 33419311, 2020). "Commensurate with activated JAK1/2 in ICB-resistant IFNγR1KO melanoma, Ruxo selectively suppressed IFNγR1KO but not scrambled control melanomas, highlighting Ruxo as a “targeted” therapy for ICB resistance." (PMID 36640142, 2023). "Unlike melanoma cells, in which GP130-IL6ST/JAK1-ROCK signaling is required for cancer cell migration, this signaling pathway is not necessary in tumor cells, whereas it is required in CAFs for ECM remodeling leading to the collective invasion of SCCs." (PMID 32546182, 2020). "RGP, VGP and MET cell lines all express both JAK1 and JAK2, further indicating that the major components of the MHC II signaling pathway are intact, regardless of the stage of melanoma progression." (PMID 25690042, 2015).
COVID-19 (95 papers, 2020 to 2025). A disease caused by infection with severe acute respiratory syndrome coronavirus 2. "This was further supported in a follow-up study of 24,202 COVID-19 cases that also identified a SNP in the JAK1 locus associated with disease severity." (PMID 39756517, 2025). "For example, a SNP on the JAK1 gene (rs12046291) was associated with critical COVID-19." (PMID 38268924, 2023). "Baricitinib is a JAK1/2 inhibitor; an immunomodulator with anticytokine properties that stifles immunologic response making it useful for diseases associated with excessive cytokine release, like COVID-19 and RA." (PMID 36199657, 2022). "Functionally, relevant mutations and polymorphisms in JAK family proteins, including TYK2, JAK1, JAK2, and JAK3, have been associated with diverse immune-related diseases and have now been implicated in COVID-19 severity and susceptibility." (PMID 40410684, 2025). "In conclusion, reduced risk of death in CIS-responders underlines the usefulness of CIS for the assessment of hyperinflammatory disorders, such as COVID-19, under JAK1/2 inhibitor therapy." (PMID 40430208, 2025). "pure JAK1 inhibitors like Upadacitinib haven’t seen widespread COVID-19 use, the therapeutic potential of this drug against Covid needs to be investigated." (PMID 40410684, 2025). "Beneficial effects of ruxolitinib, a JAK1/2 inhibitor, have also been reported in severe COVID-19 cases." (PMID 38979496, 2024). "Some literature suggests the treatment of patients with COVID-19 can be performed by JAK1/2 inhibitors." (PMID 37853311, 2023). "In the case of JAK1/2 inhibitors, baricitinib received an emergency use authorization to cure COVID-19 in 2020." (PMID 37261341, 2023). "The ‘dark’ genes JAK1 and OAS2 encoded the proteins JAK and 2’-5’OAS (2’-5’-Oligoadenylate synthetase) in the JAK-STAT signaling pathway in the Coronavirus disease—COVID-19, respectively." (PMID 37853311, 2023). "We sought to evaluate efficacy and safety of the Janus Kinase 1/2 inhibitor ruxolitinib, employing the previously developed COVID-19 Inflammation Score (CIS) in a prospective multicenter open label phase II trial (NCT04338958)." (PMID 37507425, 2023). "Since his latest exacerbation of behavioral symptoms were likely triggered by COVID-19, baricitinib, a JAK1/2 inhibitor, was started and provided some symptomatic relief." (PMID 36579544, 2022). "Proof of concept was demonstrated with the JAK1/JAK2 inhibitor baricitinib, which improved recovery time among patients with COVID-19–associated pneumonia when added to remdesivir." (PMID 36226977, 2022). "Third, a board range of cytokines induced in patients with severe COVID-19, including IL-2, IL-7 and IL-6 family cytokines, employ JAK1 for signal transduction." (PMID 35317858, 2022). "The current findings support the use of immunosuppressive therapy in moderate to severe hospitalized COVID-19 patients using a combination of corticosteroids, remdesivir, and a JAK1/2 inhibitor." (PMID 35079694, 2022). "Initial case series and explorative studies found that patients with severe COVID-19 who were treated with eculizumab, including in combination with the JAK1/2 inhibitor ruxolitinib, experienced more positive clinical outcomes." (PMID 36304162, 2022). "Baricitinib inhibits this pathway selectively by blocking JAK-1 and-2 which results is down-regulation of cytokine storm in COVID-19." (PMID 33962573, 2021). "A combined treatment with the JAK1/2 inhibitor Baricitinib, and Remdesivir in COVID-19 patients promotes recovery and reduces COVID-19 mortality rates compared to Remdesivir treatment alone." (PMID 34248930, 2021). "On the other hand, baricitinib, a high-affinity JAK1/2 inhibitor, has been shown to improve some clinical and laboratory parameters (including C-reactive protein levels) in a pilot study of COVID-19 cases." (PMID 33584343, 2021).
COVID-19 (continued). "An example of a successful combinatorial antiviral therapy and immunomodulatory approach is Remdesivir and Barcitinib (JAK-1 inhibitor), which has been shown to be effective in reducing clinical severity and mortality rates in COVID-19 patients." (PMID 34205098, 2021). "Adaptive COVID-19 treatment trial-2 (ACCT-2) has tested the benefit of combining baricitinib (a specific inhibitor of Janus kinase-1 and Janus kinase-2) with remdesivir in critically ill patients of COVID-19." (PMID 34159203, 2021). "Fedratinib is a highly selective inhibitor of JAK2 and a modest inhibitor of JAK1 and JAK3 showed efficacy against cytokine storms caused by COVID-19 via the downregulation of T helper-17-associated cytokines." (PMID 34359931, 2021). "The oral JAK1/JAK2 inhibitor baricitinib has been intended to use as an anti-inflammatory or anti-cytokine agent in COVID-19 in a few setups across the world." (PMID 33962573, 2021). "Baricitinib, another Jak1/Jak2 inhibitor, is also under investigation for COVID-19 patients (NCT04340232)." (PMID 33324210, 2020). "For example, the Jak1/Jak2 inhibitor ruxolitinib is currently under investigation in clinical trials in severe COVID-19 patients (NCT04338958; NCT04359290; NCT04348071)." (PMID 33324210, 2020). "Ruxolitinib is another JAK1/2 inhibitor that has shown promise to limit hyperinflammation in COVID-19 in a pilot case series of 105 COVID-19 patients." (PMID 33375371, 2020). "A multicenter, single-blind, randomized controlled trial showed that ruxolitinib (JAK1/2 inhibitor) recipients with COVID-19 had a numerically faster clinical improvement." (PMID 32854750, 2020). "Elevated serum of interferon (IFN)-γ has been found in patients ARDS in COVID-19, and it exerts multiple effects through the JAK1/JAK2 signaling resulting to the activation of a inflammatory factors downstream cascade." (PMID 33323549, 2020). "However, baricitinib, a JAK inhibitor acting on JAK1/2 identified as a candidate medicine using artificial intelligence, is used for the treatment of severe pneumonia in patients with COVID-19, together with remdesivir, an antiviral medicine." (PMID 38634132, 2024). "Furthermore, the inflammatory response of COVID-19 exhibits a similar macrophage-derived cytokine profile as hemophagocytic lymphohistiocytosis, which is responsive to the selective JAK1/JAK2 inhibitor ruxolitinib." (PMID 36226977, 2022). "Our dataset supports previous COVID-19 drug repurposing studies and can increase the confidence in certain drugs consistently proposed for repurposing, including the JAK1 inhibitor Baricitinib, retinoic acid receptor agonist Acitretin, and ATPase inhibitors digoxin and ouabain." (PMID 35337019, 2022). "Other anti-inflammatory agents were also tested in their effectiveness by repurposed drugs for COVID-19 therapy and involved positive results under mediators such as inhibitors of C5, IL-1, JAK1, JAK2 and IL-33 and related to reducing release of TNF-α and IL-1β." (PMID 35843719, 2022). "On the basis of this background information, we hypothesized that the JAK1/2-STAT1/2/3 pathways are the primary mediators of the effects of COVID-19–induced cytokines in driving APOL1 expression." (PMID 35472001, 2022). "In general, the use of ruxolitinib has been authorized in COVID-19 patients with respiratory insufficiency, and clinical evidence has suggested that this inhibitor of JAK1 and JAK2 can reduce inflammatory pulmonary reaction and potentially prevent the use of intensive care." (PMID 35337171, 2022). "Also, approaches combining JAK1/2 inhibitors with blockade of C5a with eculizumab are being considered as a treatment of severe pulmonary damage in COVID-19 patients." (PMID 34293006, 2021).
COVID-19 (continued). "The JAK2 inhibitor fedratinib has been reported to reduce mortality from COVID-19 and ruxolitinib (a tyrosine kinase inhibitor) inhibits viral infection by inhibition of JAK1 and JAK2 and other JAK inhibitors can block cytokine release associated with COVID-19-induced cytokine storm." (PMID 34067609, 2021). "Indeed, dexamethasone and baricitinib (JAK1/2 inhibitor) have been shown to improve outcomes in COVID-19 patients." (PMID 34746028, 2021). "This promising path could be further examined in clinical trials that include individuals with DS, as JAK1/2 inhibition may be even more beneficial in COVID-19 patients with DS." (PMID 34248930, 2021). "Baricitinib, a JAK1/JAK2 inhibitor has been found to be effective in COVID-19 treatment." (PMID 33668085, 2021). "Specifically, cancer therapeutics have been hypothesized to treat cytokine release syndrome in patients with COVID-19, and the JAK1/2 inhibitor, ruxolitinib, is currently being used in a Phase III trial to assess its efficacy." (PMID 33230423, 2020). "Baricitinib, a JAK1/JAK2 inhibitor, has been used for treating severe COVID-19 cases requiring hospitalization." (PMID 38979496, 2024). "•The expressions of other genes that are not included in the potential main pathway of steroids' anti-inflammatory effects, yet affected by steroid binding and its receptors, i.e., DUSP-1, JAK-1 and MAPK-1, were dramatically higher in mild COVID-19 patients." (PMID 38187222, 2024). "By use of ingenuity pathway analysis (IPA) and publicly available ChIP-Seq of STAT1, interferon (INF)-JAK1/2-induced STAT1 signaling pathway is predicted to induce complement C3 expression and its activation in COVID-19 infected human lung epithelial cells." (PMID 38538870, 2024). "Three FDA-approved drugs for other indications were repurposed for COVID-19 treatment: Baricitinib, Ruxolitonib, and Tofacitinib, which target JAK1/JAK2, JAK1/JAK2, and JAK1/JAK3, respectively." (PMID 39599762, 2024). "A recent study showed that severe COVID-19 patients with primary thrombocythemia and IPF were significantly improved by the treatment of JAK1/2 inhibitor Ruxolitinib." (PMID 36903446, 2023). "Baricitinib is a selective JAK1/JAK2 inhibitor approved for the treatment of RA and has shown significant morbidity and mortality benefits in COVID-19." (PMID 36987476, 2023). "Ruxolitinib, the third most-screened medicine, is known for inhibiting JAK1 and JAK2 and thereby inhibiting tumor invasion and tumorigenesis in human GBM, and it was also employed during COVID-19 for combined antiviral and anti-inflammatory therapy." (PMID 36834974, 2023). "Ruxolitinib is a selective JAK1 and JAK2 inhibitor that also has modest selectivity against tyrosine kinase (TYK) 2 and JAK3 and shows benefit in COVID-19." (PMID 36987476, 2023). "Tocilizumab, a monoclonal anti-IL6 receptor antibody, and baracitinib, a monoclonal antibody that inhibits JAK1 and JAK2 (which are activated in response to IL6 signaling), have also demonstrated initial clinical efficacy in COVID-19 patients." (PMID 37090709, 2023). "Results from a RCT that examined tofacitinib, a selective inhibitor of JAK1 and JAK3, in the setting of COVID-19, have also been reported." (PMID 36304162, 2022). "Ruxolitinib, as a selective inhibitor of JAK1 and JAK2, is able to counteract hyperinflammation and is currently being investigated for use in treating COVID-19 infected patients." (PMID 35337171, 2022). "In hospitalized patients with mild-to-moderate COVID-19, the combination of SOC with anti-IL-17A or anti-IL-6R therapy were superior or comparable to the combination with JAK1/JAK2 inhibitor, and all three were superior to SOC alone." (PMID 36001576, 2022). "Given the prior use of multiple immunomodulating agents targeting various signaling pathways, after he suffered COVID-19, we attempted to block down-stream type 1 IFN signaling pathways with the use of baricitinib, a JAK1/2 inhibitor." (PMID 36579544, 2022).
COVID-19 (continued). "JAK1 and JAK2 inhibitors came out also as interesting candidates for repurposing, with several inhibitors being actively tested in COVID-19 patients." (PMID 34293006, 2021). "Baricitinib is a selective inhibitor of JAK1 and JAK2 and believed to interfere with the signaling of key cytokines that are produced abundantly in COVID-19, including IL-2, IL-6, IL-7, and granulocyte monocyte colony-stimulating factor." (PMID 34359931, 2021). "Several JAK inhibitors, e.g., ruxolitinib (JAK1/2), baricitinib (JAK1/2), and tofacitinib (JAK1/2/3, TYK2), are currently in clinical trials for COVID-19." (PMID 34439323, 2021). "Also, JAK1/2 pathways were also reported as important targets, and their inhibitors, ruxolitinib, tofacitinib, baricitinib and fostamatinib, could be effective for COVID-19 treatment." (PMID 33413329, 2021). "Tofacitinib, which inhibit JAK1, JAK2, and JAK3, and baricitinib and ruxolitinib, both acting against JAK1 and JAK2 are currently under investigation for COVID-19." (PMID 34421600, 2021). "Baricitinib is a selective JAK1 and JAK2 inhibitor and inhibits JAK1/2-dependent cytokines (e.g., IL-6 and interferon [IFN]-γ), typically involved in COVID-19 inflammation." (PMID 34356617, 2021). "Several authors suggest the use of JAK inhibitors (JAKi) in the treatment of COVID-19 as in the case of Baricitinib, a JAK inhibitor targeting JAK1 and JAK2, mechanistically able to inhibit the signaling of many COVID-19-related cytokines." (PMID 32973818, 2020). "Using a newly developed COVID-19 Inflammation Score (CIS), patients were prospectively stratified for targeted inhibition of cytokine signalling by the Janus Kinase 1/2 inhibitor ruxolitinib (Rux)." (PMID 32518419, 2020). "Although various anti-cytokine drugs which act against interleukin (IL) -6, Janus kinase 1 and 2 have been proved to be effective against severe COVID-19, these were not available at the time of study period." (PMID 38771836, 2024). "Furthermore, our findings showed that other genes, including TSC22D3, DUSP-1, JAK-1, and MAPK-1 expressions, were significantly elevated in mild COVID-19." (PMID 38187222, 2024). "At the University Hospital Marburg, following the successful individual treatment of a single patient, we conducted a non-randomized phase-II trial of the JAK1/2-Inhibitor Ruxolitinib in critically ill COVID-19 patients requiring mechanical ventilation." (PMID 37293294, 2023). "Baricitinib blocks this pathway by inhibiting JAK-1 and JAK-2, thereby downregulating the inflammatory cytokine storm in COVID-19, and may have additional antiviral activity." (PMID 38050265, 2023). "Different JAK inhibitors have been proposed for the treatment of COVID-19, namely: JAK1/JAK2/TYK2 inhibitors (e.g., baricitinib, ruxolitinib), selective JAK2 inhibitors (e.g., fedratinib), and - more recently - JAK1/JAK3 inhibitors (e.g., tofacitinib)." (PMID 35340805, 2022). "All signaling molecules of the IFN-I downstream pathway and IRFs (i.e., JAK-1, TYK-2, STAT-1, STAT-2, IRF-3, and IRF-7) showed very reduced expression levels in COVID-19 patients with the severe condition compared to healthy individuals at both RNA and protein levels." (PMID 35842705, 2022). "When compared to other drug therapy for COVID-19, this JAK1/2 inhibitor has no clotting adverse drug effect, which contributes to its safety profile." (PMID 36199657, 2022). "Inhibits JAK3, JAK1, JAK2, and to a lesser extent TYK2 and inhibits receptor signaling through pairs of JAK2 and because it can suppress the production of different cytokines, such as IL-2, IL-7 and IL-6 can used for patients with COVID-19." (PMID 36111104, 2022). "Baricitinib, specifically, is an orally administered inhibitor of JAK1 and JAK2 that blocks the intracellular signaling pathways of cytokines, which are known to be elevated in severe COVID-19, including IL-2, IL-6, interferon-γ and granulocyte-macrophage colony-stimulating factor." (PMID 36304162, 2022).